RNU6-1103P (RNA, U6 small nuclear 1103, pseudogene)
Gene: Small nuclear RNA gene on chromosome 7 (24,537,332 to 24,537,438, forward strand). Ensembl gene ENSG00000206877.
Homologues: Orthologues: chimpanzee U6 (96% identical), mouse Gm24856 (93% identical), pig U6 (91% identical), guinea pig U6 (88% identical), rabbit U6 (81% identical). Paralogues in human: RNU6-1 (92% identical), RNU6-15P (92% identical), RNU6-2 (92% identical), RNU6-3P (92% identical), RNU6-4P (92% identical), RNU6-5P (92% identical), RNU6-6P (92% identical), RNU6-9 (92% identical), RNU6-10P (91% identical), RNU6-12P (91% identical), RNU6-13P (91% identical), RNU6-16P (91% identical), and 1284 more.